MT-ND6 (mitochondrially encoded NADH:ubiquinone oxidoreductase core subunit 6)
Description:
Core subunit of the mitochondrial membrane respiratory chain NADH dehydrogenase (Complex I) which catalyzes electron transfer from NADH through the respiratory chain, using ubiquinone as an electron acceptor. Essential for the catalytic activity and assembly of complex I.
Synonyms: ND6; NAD6; formerly MTND6
Tractability: Small molecule: an approved drug acts on it; a structure with a bound ligand is known. Antibody: UniProt predicts a signal peptide or a membrane-spanning region.
Gene: Protein-coding gene on chromosome MT (14,149 to 14,673, reverse strand). Ensembl gene ENSG00000198695.
Subcellular location: Mitochondrion inner membrane
Pathways (Reactome):
Metabolism: Complex I biogenesis; Respiratory electron transport
Metabolism of proteins: Mitochondrial protein degradation; Mitochondrial translation termination
Gene Ontology:
Molecular function: NADH dehydrogenase (ubiquinone) activity
Biological process: mitochondrial electron transport, NADH to ubiquinone; mitochondrial respiratory chain complex I assembly; aerobic respiration; proton motive force-driven mitochondrial ATP synthesis; proton transmembrane transport
Cellular component: mitochondrial inner membrane; mitochondrion; respiratory chain complex I
Gene-disease validity (ClinGen):
ClinGen rates the evidence that MT-ND6 causes each of these diseases.
Leigh syndrome (mitochondrial): Definitive. A progressive neurological disease defined by specific neuropathological features associating brainstem and basal ganglia lesions.
mitochondrial disease (mitochondrial): Definitive.
Homologues: Orthologues: chimpanzee MT-ND6 (96% identical), macaque ND6 (79% identical), rabbit MT-ND6 (66% identical), pig ND6 (58% identical), guinea pig MT-ND6 (52% identical), mouse mt-Nd6 (52% identical), rat Mt-nd6 (49% identical), tropical clawed frog ND6 (34% identical), zebrafish mt-nd6 (32% identical).
Diseases named in the same sentence as MT-ND6 in open-access papers:
MT-ND6 is named in the same sentence as 99 diseases in open-access papers, as found by Europe PMC text mining. Sharing a sentence is not in itself a finding about the gene and the disease. The quoted sentences say what the papers report.
Leber hereditary optic neuropathy (33 papers, 2009 to 2025). Leber's hereditary optic neuropathy (LHON) is a mitochondrial neurodegenerative disease affecting the optic nerve and often characterized by sudden vision loss in young adult carriers. "In this study, we demonstrate early mitochondrial changes in the retina and the prelaminar ON of mouse models of hereditary optic atrophy carrying mutations in the Opa1 and MT-Nd6 genes." (PMID 39659974, 2024). "m.14597A>G (p.Ile26Thr) in the MT-ND6 gene was reported to cause Leberʼs hereditary optic neuropathy (LHON) or dementia/dysarthria." (PMID 34045482, 2021). "The m.14487T>C mutation in the mtDNA MT-ND6 gene has been reported in the neurological disorders of optic atrophy, bilateral striatal necrosis, childhood-onset dystonia, progressive myoclonic epilepsy, and LS." (PMID 34025555, 2021). "A mouse model has been created with a homoplasmic m.13997G>A mutation within MTND6, which causes an amino acid substitution (p.Pro25Leu) similar to the m.14600G>A mutation previously reported in a family with Leigh syndrome and optic atrophy." (PMID 28093355, 2017). "Furthermore, MT-ND1, MT-ND6 gene mutations and a 4-base-pair deletion in the cytochrome B gene were found in patients with parkinsonism associated with optic atrophy, myoclonic epilepsy and SLEs, typical PMDs red flags." (PMID 38069070, 2023). "Mutations in MT-ND6 have been found in association with several diseases, including Leber’s Hereditary Optic Neuropathy (LHON), where retinal ganglion cells are affected leading to loss of visual acuity, and Leigh Syndrome, a primarily neurological condition with paediatric onset." (PMID 31835862, 2019). "Next, we tried to install two mutations at GC context in MT-ND4 and MT-ND6 that have been linked to human diseases including Leber hereditary optic neuropathy (LHON) and Leigh syndrome, which are both devastating genetic diseases with no effective therapy." (PMID 36797253, 2023). "Most MT-ND6 mutations cause Leber hereditary optic neuropathy (LHON), but some mutations have been reported to lead to LS." (PMID 34045482, 2021). "In addition, one patient was diagnosed with Leber hereditary optic neuropathy (LHON), which was genetically confirmed (m.14568A > G mutation in MT-ND6)." (PMID 36298623, 2022). "In addition, a mutant mtDNA mouse model for MT‐ND6 CI subunit for Leber's hereditary optic neuropathy (LHON) was also created and explored." (PMID 31916679, 2020). "Leber’s hereditary optic neuropathy (LHON), a maternally inherited blinding disorder, is associated with three common mitochondrial DNA (mtDNA) point mutations affecting complex I (m.3460G>A/MT-ND1, m.11778G>A/MT-ND4, m.14484T>C/MT-ND6) in 90% of cases." (PMID 24884847, 2014). "Leber hereditary optic neuropathy (LHON) is the typical single organ involvement mitochondrial disorder caused by mtDNA point mutations such as genevariation on m.3460G → A MT-ND1, m.11778G → A MT-ND4, and m.14484 T → C MT-ND6." (PMID 40536597, 2025). "Leber hereditary optic neuropathy (LHON) is an inherited optic neuropathy that develops predominantly as a consequence of three mtDNA point pathogenic variants, namely m.3460G > A (MT-ND1), m.11778G > A (MT-ND4), and m.14484T > C (MT-ND6)." (PMID 36294366, 2022). "The three primary mutations (m.3460G>A in the MT-ND1 gene, m.11778G>A in the MT-ND4 gene, and m.14484T>C in the MT-ND6 gene) on mitochondrial DNA (mtDNA) have been identified to be the essential factors for Leber hereditary optic neuropathy (LHON, OMIM 535000)." (PMID 22110754, 2011).
Leigh syndrome (15 papers, 2012 to 2025). "The findings presented in the manuscript, strongly support pathogenicity of the m.14430 A > C variant in MT-ND6 as a cause of Leigh syndrome in this patient." (PMID 38571879, 2024). "The combined clinical, genetic, and biochemical findings suggest that the novel MT-ND6 variant is the likely cause of Leigh syndrome in this patient." (PMID 38571879, 2024). "At least six other variants in MT-ND6 have been associated with Leigh syndrome, including the m.14430A>G, p.(Trp82Arg) variant recently reported in a patient with complex 1 deficiency, affecting the same nucleotide with a different amino acid change." (PMID 38571879, 2024). "Here we describe a novel, likely pathogenic variant in MT-ND6, encoding the ND6 subunit of complex I in a patient with Leigh syndrome." (PMID 38571879, 2024). "An 18-month-old male patient (ID: P13) with early-onset psychomotor retardation and developmental regression had a missense mutation (m.14430A > G, p.W82R) with mutation load of 91.3% in the MT-ND6 gene that was diagnosed with Leigh syndrome." (PMID 34490048, 2021).
breast carcinoma (10 papers, 2016 to 2024). "In a study conducted on a Polish population, a total of 28 changes were detected in MT-ND1, MT-ND2, MT-ND3 and MT-ND6 in breast cancer cells, which were described in databases as polymorphisms." (PMID 37189801, 2023). "Another mutation in MT-ND6 (C12084T) was identified and correlated with metastatic capacity in a breast cancer cell line." (PMID 35163579, 2022). "Ishikawa and co-workers demonstrated that the MT-ND6 insertion mutation (13885insC) suppressed complex I activity and induced ROS production, resulting in the induction of cell metastasis in lung and breast cancer cells." (PMID 35163579, 2022). "Five mitochondrial genes (MT-ND4, MT-ND1, MT-ND3, MT-ND6, and MT-ND2), which were identified as key genes of the complex I biogenesis pathway by Pathformer, were also reported to be associated with breast cancer prognosis." (PMID 38741230, 2024).
Insulin resistance (8 papers, 2016 to 2025). Increased resistance towards insulin, that is, diminished effectiveness of insulin in reducing blood glucose levels. "This was supported by the finding that both MT-ND6 knockout mice and mice subjected to a diet that led to methylation at MT-ND6 induced by DNMT1 had a higher likelihood of developing systemic insulin resistance than the control." (PMID 36866104, 2023).
steatosis (8 papers, 2015 to 2023). Increased lipid within the cytoplasm of cells. "For instance, it has been observed that biopsy-proven NASH patients had higher methylation levels of Mitochondrially encoded NADH dehydrogenase 6 (MT-ND6) than individuals with simple steatosis and they correlated with NAFLD activity score (NAS)." (PMID 32340286, 2020). "In particular, NASH patients are characterized by severely enhanced hepatic DNMT levels, whereby inducing a higher methylation pattern of specific genes, including the mitochondrially encoded NADH dehydrogenase 6 (MT-ND6) compared to those with simple steatosis." (PMID 34829753, 2021). "Liver methylation of NADH dehydrogenase 6 (MT-ND6) correlates with NAFLD severity, resulting in significantly lower expression of MT-ND6 mRNA in NASH than in patients with simple steatosis." (PMID 27657051, 2016).
diabetes (6 papers, 2015 to 2024). "The m.14577T > C mutation in MT-ND6, which encodes NADH-ubiquinone oxidoreductase chain 6, a core subunit of complex I, was associated with diabetes mellitus." (PMID 36557887, 2022).
lung carcinoma (6 papers, 2021 to 2023). "The missense and nonsense mutations in MT-ND6 enhanced tumor invasion and migration, as also demonstrated in the A549 lung cancer cell line." (PMID 35454769, 2022).
MELAS (6 papers, 2016 to 2025). "For example, about 80% of patients with MELAS harbor the m.3243A>G mutation in the mitochondrial tRNALeu(UUR) gene (MTTL1), whereas mutations in polypeptide-coding genes, including subunits 1, 5, and 6 of complex I (MT-ND1, MT-ND5, and MT-ND6), have also been identified in MELAS." (PMID 34025555, 2021).
Obesity (4 papers, 2013 to 2025). Accumulation of substantial excess body fat. "Moreover, SNPs in mitochondrial genes also demonstrate sex-specific associations: the MT-ND6 14431T>C mutation correlates with obesity in males, whereas the MT-TF 152T>C mutation elevates obesity risk in females." (PMID 41340654, 2025).
Optic neuropathy (4 papers, 2020 to 2024). "Most of them have LHON syndrome with isolated optic neuropathy due to the prevalent mutations m.11777G > A in MT-ND4, m.3460G > A in MT-ND1, or m.14484 T > C in MT-ND6." (PMID 31996177, 2020).
lung adenocarcinoma (3 papers, 2015 to 2022). A carcinoma that arises from the lung and is characterized by the presence of malignant glandular epithelial cells. "Similarly, MT‐ND6 nonsense and missense mutations in lung adenocarcinoma cybrids also activate the Akt pathway in a ROS‐dependent manner." (PMID 35842901, 2022). "A significant correlation between missense and nonsense MT‐ND6 mutations and pathological grade, tumour stage and lymph node metastasis were reported in human lung adenocarcinoma samples." (PMID 35842901, 2022). "Furthermore, the migratory distance of the lung adenocarcinoma cybrids was significantly greater in those with MT‐ND6 nonsense and missense mutations, suggesting the promotion of migration and invasion by these mutations." (PMID 35842901, 2022).
colorectal cancer (2 papers, 2017 to 2025). A primary or metastatic malignant neoplasm that affects the colon or rectum. "Increased levels of mitochondrial gene expression have also been found in studies of colorectal cancer, where mt-ND6 and mt-ND1 mRNA levels were significantly increased in growing adenocarcinomas." (PMID 29164120, 2017).
dementia (2 papers, 2021). Loss of intellectual abilities interfering with an individual's social and occupational functions. "A group of mitochondria proteins related to energy generation were observed in these same pathways/hubs that were previously shown to have AD/dementia/amyloidosis associations including MT-ND1, MT-ND6, and MT-CO1." (PMID 33946285, 2021).
non-alcoholic steatohepatitis (2 papers, 2020 to 2021). "Analysis of mtDNA methylation in liver biopsies from patients with non-alcoholic steatohepatitis revealed that MT-ND6 methylation was significantly higher than that observed in individuals with simple steatosis." (PMID 33925624, 2021).
psoriasis (2 papers, 2022 to 2025). An autoimmune condition characterized by red, well-delineated plaques with silvery scales that are usually on the extensor surfaces and scalp. "P. clypearia may ameliorate inflammation in psoriasis mice by modulating genes such as Hspa1a, Hspa1b, mt-Nd4l, mt-Nd5, mt-Nd6, Bcl2, Asns, Trib3, and associated pathways related to energy metabolism, cell growth, and apoptosis." (PMID 41385507, 2025). "Our study demonstrated that IMQ downregulated mt-ND4L, mt-ND5, and mt-ND6, while ESW administration could reverse this effect, indicating that ESW may improve psoriasis inflammation by regulating mitochondria and energy metabolism." (PMID 41385507, 2025). "The results indicated that P. clypearia may affect the energy metabolism, cell growth and apoptosis by regulating genes such as Hspa1a, Hspa1b, mt-Nd4l, mt-Nd5, mt-Nd6, Bcl-2, Asns, Trib3, GzmA, CTSG, etc, thereby mitigating psoriasis-related inflammation." (PMID 41385507, 2025).
adenoma (1 paper, 2010). A neoplasm arising from the epithelium. "Moreover, variants A14633G and 14652delA in the MT-ND6 gene was found only in the polyvillous adenomas, a designated subset of villous adenomas." (PMID 20929553, 2010).
asthma (1 paper, 2024). "Previously, rs28357671, located on the MT-ND6 gene, was associated with atopic dermatitis (AD) and asthma." (PMID 38395967, 2024).
breast tumours (1 paper, 2014). "The purpose of this study was to analyze mutations in MT-ND1, MT-ND2, MT-ND3 and MT-ND6 genes and their effect on the biochemical properties, structure and functioning of proteins in patients with breast tumours." (PMID 24414975, 2014).
encephalomyopathy (1 paper, 2019). "This gene encodes the ND6 subunit that seems to be important for the assembly of Complex I; in humans various point mutations of the MT-ND6 gene affect NADH dehydrogenase activity and are associated with diseases such as Leber’s optic neuropathy, encephalomyopathy, and stroke-like episodes." (PMID 31703111, 2019).
liver disease (1 paper, 2022). "In addition, methylation of the liver mitochondrial encoded NADH dehydrogenase 6 (MT-ND6) associated with liver disease severity." (PMID 36093112, 2022).
Mitochondrial myopathy (1 paper, 2024). "MT-ND6 mutations can also be pathogenic and are associated with conditions like LHON and mitochondrial myopathy." (PMID 39525159, 2024).
nonsyndromic deafness (1 paper, 2014). An auditory system disease that is associated with permanent hearing loss caused by damage to structures in the inner ear and/or the middle ear, which is not associated with other signs and symptoms. "Similar result was reported in the case of MT-TS1 7511T>C associated with nonsyndromic deafness that significant reduction in the level of MT-ND1 mRNA was found but not MT-ND6 mRNA." (PMID 25474306, 2014).
parathyroid carcinoma (1 paper, 2021). "Sequencing of mtDNA in the tumors developed by patient II.2 revealed the presence of the somatic transition m.14387A>G/MT-ND6 within the thyroid infiltration of the parathyroid carcinoma." (PMID 34831144, 2021).
tumor (24 papers, 2009 to 2026). "While genetic analyses revealed the presence of gene mutations that could be considered predisposing factors for HCC, sequencing of mtDNA unveiled a new mutation of the tumor’s mitochondrial gene ND6 (MT-ND6)." (PMID 40157968, 2025). "In addition, tumor cells of PTR1 and other regions had different mutations at MT-ND6(chrM:14504 - PTR1) and MT-ND3(chrM:10396 - PTR2-PTR3, LyM, LM), respectively." (PMID 35974387, 2022). "It is noteworthy that these three, along with MT-ND6, were heteroplasmic in all tumor samples, but not in all internal controls." (PMID 31673122, 2019). "MTND6P4 may regulate its parental gene MTND6 and hypomethylation and subsequent overexpression of MTND6P4 may lead to changes in oxidative phosphorylation activies, glycolysis and brain microenvironment contributing to growth advantages to tumours via upregulation of MTND6." (PMID 35058523, 2022).
cancer (15 papers, 2008 to 2026). A tumor composed of atypical neoplastic, often pleomorphic cells that invade other tissues. "During oxidative stress and hypoxia, increased mitochondrial MDM2 represses NADH-dehydrogenase 6 (MT-ND6) transcription and decreases respiratory complex I activity, resulting in enhanced cancer cell migration and invasion." (PMID 32397368, 2020). "In addition, six transcripts (MT-ATP6, MT-CO1, MT-CYB, MT-ND1, MT-ND6, and MT-RNR1) were quantified in 62 cancer tissues by real-time RT-PCR." (PMID 18842121, 2008).
myopathy (3 papers, 2015 to 2022). A disease of the muscle in which the muscle fibers do not function properly. "A heteroplasmic m.14512_14513del MT-ND6 variant was identified in Patient 1 who presented with exercise intolerance, mild myopathy, and hyperCKaemia." (PMID 32158465, 2020).
psychiatric disorder (2 papers, 2025). A disorder characterized by behavioral and/or psychological abnormalities, often accompanied by physical symptoms. "Moreover, mutations in MT-ND6 and MT-ND5, both components of NADH dehydrogenase, have been associated with various psychiatric disorders." (PMID 40495250, 2025).
heart disease (1 paper, 2022). "In addition, two families with HCM had mutations in mitochondrial genes MT-CO1 and MT-ND6; both previously implicated in heart disease, although heteroplasmy proportions are yet to be determined in multiple tissue samples." (PMID 36357925, 2022).
Kidney (1 paper, 2022). "The amino acid change associations were previously predicted between Prost-AdenoCA and MT-ND5 (13789 T > C, Y485H), Kidney-RCC and MT-ND6 (14178 T > C, I166V), and Kidney-ChRCC and MT-ATP6 (8584 G > A, A20T)." (PMID 35183124, 2022).
movement disorder (1 paper, 2024). Neurological conditions resulting in abnormal voluntary or involuntary movement, which may impact the speed, fluency, quality and ease of movement. "A girl with a paediatric onset movement disorder with choreiform movements and dystonic posturing of the hands and head, developmental regression and Parkinsonian symptoms had the m.14484T>C variant in the MT‐ND6 gene." (PMID 39095335, 2024).
MT-ND6 also shares sentences with these, for which no sentence is quoted: infection (7 papers); Lewis lung carcinoma (5); optic atrophy (5); Parkinson disease (5); glioma (4); mitochondrial disease (4); autosomal dominant optic atrophy (3); colon cancer (3); deafness (3); hereditary optic neuropathy (3); MELAS syndrome (3); type 2 diabetes (3); COVID-19 (2); fibrosarcoma (2); glioblastoma (2); hepatocellular carcinoma (2); Huntington disease (2); Hypertension (2); metabolic disorders (2); neurodegenerative disease (2); neurological diseases (2); osteosarcoma (2); Sepsis (2); adenocarcinoma (1); alcoholic fatty liver disease (1); Alzheimer disease (1); amyloidosis (1); amyotrophic lateral sclerosis (1); antineutrophil cytoplasmic antibody-associated vasculitis (1); Anxiety (1).
A further 39 diseases each share a sentence with MT-ND6 in 1 paper.